ZNF354B (zinc finger protein 354B)
Description:
Transcriptional repressor that binds DNA upon activation by RAS proteins signal transduction to initiate transcriptional silencing through the recruitment of additional DNA-binding proteins, multisubunit complexes and chromatin-modifying activities to establish a platform for DNMT1 recruitment.
Synonyms: KID2; FLJ25008
Tractability: PROTAC: UniProt records ubiquitination sites on it; ubiquitination databases record sites on it.
Gene: Protein-coding gene on chromosome 5 (178,859,953 to 178,888,122, forward strand). Ensembl gene ENSG00000178338.
Subcellular location: Nucleus
Subcellular location (Human Protein Atlas): Nucleoplasm
Pathways (Reactome):
Gene expression (Transcription): Generic Transcription Pathway
Gene Ontology:
Molecular function: chromatin binding; DNA-binding transcription factor activity, RNA polymerase II-specific; RNA polymerase II cis-regulatory region sequence-specific DNA binding; transcription corepressor activity
Biological process: negative regulation of transcription by RNA polymerase II; regulation of transcription by RNA polymerase II; regulation of DNA-templated transcription
Cellular component: nucleus
Genetic constraint (gnomAD): Loss-of-function variants: 21 observed, 25.62 expected, observed/expected ratio (o/e) 0.82, 90% interval 0.58 to 1.18. The upper end of that interval is the gene's LOEUF score, 1.18, which puts it in group 5 of 6, group 1 being the genes least tolerant of losing a copy. Missense variants: 610 observed, 725.53 expected, observed/expected ratio (o/e) 0.84, 90% interval 0.79 to 0.9. Synonymous variants: 257 observed, 241.33 expected, observed/expected ratio (o/e) 1.06, 90% interval 0.96 to 1.18.
Homologues: Orthologues: chimpanzee ZNF354B (99% identical), macaque ZNF354B (96% identical), dog ZNF354B (89% identical), pig ZNF354B (88% identical), rabbit ZNF354B (85% identical), guinea pig ZNF354B (84% identical), rat Znf454 (82% identical), mouse Zfp354b (81% identical). Paralogues in human: ZNF354A (85% identical), ZNF658 (46% identical), ZNF879 (45% identical), ZNF717 (44% identical), ZNF726 (44% identical), ZNF7 (44% identical), ZNF708 (44% identical), ZNF484 (43% identical), ZNF728 (43% identical), ZNF254 (43% identical), ZNF595 (43% identical), ZNF33B (43% identical), and 164 more.